REG4 (regenerating family member 4)
Diseases named in the same sentence as REG4 in open-access papers (continued):
Sharing a sentence is not in itself a finding about the gene and the disease.
mucinous ovarian cancer (4 papers, 2016 to 2021). An invasive malignant neoplasm that arises from the ovary and is characterized by the presence of malignant epithelial cells that contain intracytoplasmic mucin and may resemble the epithelial cells of the endocervix or gastrointestinal tract. "This study identifies REG4 as a potential serum biomarker for histotype-specific detection of mucinous ovarian cancer and suggests serum REG4 measurement as a non-invasive diagnostic tool for postoperative follow-up of patients with mucinous ovarian cancer." (PMID 26981633, 2016). "The final candidate selection identified the Regenerating Islet-Derived Protein IV (REG4) as a potential serum biomarker for mucinous ovarian cancer histotype." (PMID 26981633, 2016). "This suggests that the REG4 concentration correlates to tumor burden better than CA125 or HE4 in mucinous ovarian cancer." (PMID 26981633, 2016). "Based on in silico analyses, we studied the expression of Regenerating Islet-Derived Protein IV (REG4) in a set of mucinous ovarian cancer tissues, patient sera and ascites fluids." (PMID 26981633, 2016). "Since our serum sample collection was limited, further analyses are needed to fully determine the role of REG4 serum measurement as a pre-operative method for mucinous ovarian cancer diagnosis." (PMID 26981633, 2016). "In conclusion, we identified REG4 as a potential biomarker for subtype specific diagnosis of mucinous ovarian cancer as well as for disease follow-up." (PMID 26981633, 2016). "Database searches identified REG4 as a potential biomarker with specificity for the mucinous ovarian cancer subtype." (PMID 26981633, 2016). "The highest level of REG4 mRNA expression was seen in mucinous ovarian cancer, while the expression level remained very low in healthy ovarian tissue." (PMID 26981633, 2016). "To analyze the potential of REG4 as a serum biomarker for mucinous ovarian cancer, we used a REG4 specific sandwich ELISA assay." (PMID 26981633, 2016). "A previous study reported high serum REG4 levels in mucinous ovarian cancer." (PMID 34577861, 2021). "Other serum markers such as CA 19.9 or REG4 that have been reported to be elevated in the sera of mucinous ovarian cancer patients may need to be incorporated into our next generation of multi-protein classifier." (PMID 29051715, 2017). "According to our results, serum REG4 analysis may also have potential for differentiation between benign and malignant mucinous neoplasms and for follow-up of mucinous ovarian cancer patients." (PMID 26981633, 2016). "We measured three biomarkers from patient sera; CA125, HE4 and REG4 and found high concentrations of REG4 in preoperative samples of mucinous ovarian cancer patients, whereas CA125 and HE4 failed to convincingly detect malignancy in these samples." (PMID 26981633, 2016). "On the other hand, addition of REG4 analysis from serum on the side of CA125 and/or HE4 could provide a possibility for postoperative follow-up of mucinous ovarian cancer patients with a confirmed diagnosis." (PMID 26981633, 2016). "Thus, REG4 serum analysis alone may not be able to distinguish between primary mucinous ovarian cancer and ovarian metastases originating from the gastrointestinal tract." (PMID 26981633, 2016).
mucinous tumors (4 papers, 2012 to 2016). "With mucinous tumors excluded, REG4 expression associated significantly with higher differentiation and low stage." (PMID 25295732, 2014). "Both samples were positive (33 pg/ml and 187 pg/ml, respectively) for REG4 protein indicating that mucinous tumor cells secrete REG4 also to the ascites fluid." (PMID 26981633, 2016). "In addition to serum samples, REG4 concentration was measured from cell-free ascites fluids of two patients with mucinous tumors (M1 and M2)." (PMID 26981633, 2016).
pancreatitis (4 papers, 2013 to 2024). Inflammation of the pancreas. "The aberrant expression of REG4 in the pancreas has been linked to both pancreatitis and pancreatic cancer." (PMID 38769308, 2024). "Taken together, our results suggest that Reg4 has therapeutic effect for pancreatitis and deepened our understanding of the mechanisms underlying Reg4 functions in pancreatitis." (PMID 38769308, 2024). "Second, Reg4 deficiency exacerbated caerulein-induced experimental pancreatitis and impaired regeneration, and these effects were attenuated by the administration of recombinant Reg4 protein." (PMID 38769308, 2024). "Herein, we knocked out Reg4 in mice to test the hypothesis that loss of Reg4 constitutes a pathogenic factor in pancreatitis." (PMID 38769308, 2024). "Intriguingly, Reg4 deficiency leads to an increase in the activation of AMPK, suggesting that AMPK/mTOR signaling may be involved in Reg4 deficiency-mediated autophagic inhibition during pancreatitis." (PMID 38769308, 2024). "The ELISA assay depicted serum levels of mice REG4 were reduced during the periods of caerulein-induced pancreatitis." (PMID 38769308, 2024). "In conclusion, our findings suggest that Reg4 exerts a therapeutic effect during pancreatitis by limiting inflammation and fibrosis and improving cellular regeneration." (PMID 38769308, 2024). "The enzyme-linked immunosorbent assay (ELISA) analysis showed that the levels of blood REG4 protein were downregulated in children with pancreatitis (PA, n = 15) compared to age-matched controls (HC, n = 30, P < 0.05)." (PMID 38769308, 2024). "IF staining showed that SOX9+ cells were reduced in the pancreases of Reg4−/− mice compared to Wt mice during pancreatitis." (PMID 38769308, 2024). "We herein showed that Reg4 constitutes a potentially novel therapeutic target in the treatment of pancreatitis by demonstrating a reduction in impaired regeneration and progressive fibrosis employing a mouse model." (PMID 38769308, 2024). "To investigate the roles of Reg4 in pancreatitis, we initially depleted the Reg4 in mice (Reg4−/−) and then established the models of pancreatitis." (PMID 38769308, 2024). "During acute pancreatitis (AP), the recombinant human REG4 protein has been shown to protect against acinar cell necrosis, but its precise roles and involved mechanisms in the pathogenesis of pancreatitis are remained poor understood." (PMID 38769308, 2024). "To examine this, we treated the Reg4−/− mice with the CXCR4 antagonist plerixafor (AMD3100) with two daily injections (2.5 mg/kg body weight) initiated 1 day before the induction of pancreatitis and which lasted until day 7 when the mice were sacrificed." (PMID 38769308, 2024). "In conclusion, our study provides evidence for the protective function of Reg4 in which this molecule attenuated inflammation, mitochondrial cell death, and fibrosis and promoted regeneration during pancreatitis." (PMID 38769308, 2024). "On the basis of this concept, we next used recombinant Reg4 (rReg4) protein therapeutically to ameliorate caerulein-induced pancreatitis." (PMID 38769308, 2024). "We first ascertained that both blood REG4 levels were reduced during pancreatitis in clinical samples." (PMID 38769308, 2024). "Mechanistically, Reg4 mediates its function in pancreatitis potentially via binding its receptor exostosin-like glycosyltransferase 3 (Extl3)." (PMID 38769308, 2024). "Herein, we sought to investigate the contribution of Reg4 to the pathogenesis of pancreatitis and evaluate its therapeutic effects in experimental pancreatitis." (PMID 38769308, 2024). "The specific knockout of Reg3b or administration of anti-Reg1, anti-Reg3a, and anti-Reg4 antibodies worsen experimental pancreatitis, while administration of recombinant Reg3a and Reg4 can significantly reduce the pancreatic damage." (PMID 37500741, 2023).
pancreatitis (continued). "Reg4 ablation may increase CXCL12/CXCR4 axis activation during pancreatitis and thereby potentially lead to stimulated TGF-β/SMADs profibrotic signaling, and this might then activate pancreatic stellate cells." (PMID 38769308, 2024). "We thus suggest Extl3 may functions as the receptor for Reg4 and mediates the activation of downstream signaling proteins during pancreatitis." (PMID 38769308, 2024). "WB analysis herein indicated that phosphorylated-AMPK (p-AMPK) increased and phosphorylated-mTOR (p-mTOR) decreased, with concomitantly reduced autophagy in the pancreases of Reg4−/− mice during pancreatitis, but these alterations were circumvented by rReg4 administration." (PMID 38769308, 2024). "Thus, Reg4 administration increased the levels of the anti-apoptotic mitochondrial molecule Bcl-2 and decreased Puma-mediated apoptosis, suggesting that Reg4 protected acinar and islet cells from cell death in pancreatitis by stabilizing mitochondria against death signals." (PMID 38769308, 2024). "EXTL3 may functions as the receptor for REG4 during pancreatitis." (PMID 38769308, 2024). "In addition, the REG4 proteins in mice pancreas were also reduced during pancreatitis." (PMID 38769308, 2024). "We visualized immune cell infiltrates during caerulein-induced pancreatitis by staining for CD45 and observed more significant CD45 infiltration in Reg4−/− mice at most time points relative to Wt mice during caerulein treatment." (PMID 38769308, 2024).
rectal cancer (4 papers, 2020 to 2022). A primary or metastatic malignant neoplasm that affects the rectum. "REG4 was the biomarker to predict concurrent chemoradiotherapy resistance in patients with rectal cancer." (PMID 35928108, 2022). "Previous research showed that the significant upregulation of the REG4 gene was closely related to the undesirable outcome and the aggressive phenotype in rectal cancer patients." (PMID 35928108, 2022). "REG4 expression was found to correlate with γ-radiation sensitivity in rectal cancer patients receiving radiotherapy." (PMID 36172286, 2022). "Moreover, REG4 was useful in predicting response to neoadjuvant chemoradiotherapy in patients with rectal cancer." (PMID 33489872, 2020). "Impressively, the regenerating family member 4 (REG4) gene was identified as the fourth most significantly positively correlated gene with MUC2 (Spearman’s correlation: 0.776) and one of the predictive factors associated with CCRT resistance in rectal cancer in our previous study." (PMID 34300195, 2021).
signet ring cell carcinoma (4 papers, 2012 to 2022). A usually aggressive, poorly differentiated invasive adenocarcinoma characterized by the presence of malignant glandular cells in which the nucleus is pressed to one side by the presence of intracytoplasmic mucus. "Histologically, REG4 protein is specifically expressed in neuroendocrine tumors and signet ring cell carcinomas of the gastrointestinal tract, pancreas, ovary, and lung." (PMID 36172286, 2022).
colon adenocarcinoma (3 papers, 2014 to 2021). "In conclusion, we have shown that in colon adenocarcinomas that express high levels of Reg4, this pathway becomes a major determinant of resistance and can affect survival in the metastatic setting." (PMID 33659040, 2021). "Our lab has previously demonstrated that exogenous Reg4 added to human colon adenocarcinoma cells leads to upregulation of the anti-apoptotic gene bcl-2 and induces resistance in vitro to ionizing irradiation and 5-FU chemotherapy." (PMID 33659040, 2021). "The significant association found in our study between Reg4, CD44, and CD44ICD gives biological credibility to this pathway within a clinical cohort of colon adenocarcinoma patients." (PMID 33659040, 2021).
diabetes (3 papers, 2016 to 2023). "The top two predictors of age were on the PRKCB and REG4 genes, which are associated with diabetes and cancer, respectively." (PMID 29754148, 2018). "It consists of 17 members, from which REG1, REG2, REG3 and REG4 have been associated with inflammation, diabetes and cancers." (PMID 26981633, 2016). "REG4 is another multifunctional protein involved in cell cycle regulation, glycolytic metabolism, and diabetes." (PMID 37064098, 2023).
gallbladder adenocarcinoma (3 papers, 2011 to 2022). A carcinoma that arises from glandular epithelial cells of the gall bladder. "REG4 expression in gallbladder adenocarcinoma is associated with a relatively favorable prognosis in patients after surgery." (PMID 33489872, 2020). "There are also studies revealing REG4 overexpression in gallbladder adenocarcinomas." (PMID 33489872, 2020).
gastric tumor (3 papers, 2008 to 2025). "Regenerating islet-derived type 4 (REG4) enhances invasiveness and migration of gastric tumor cells." (PMID 40452847, 2025).
gastritis (3 papers, 2014 to 2022). Inflammation of the stomach. "We originally reported strongly up-regulated expression of REG4 also in inflamed IBD mucosa of IBD-like foci of gastritis-induced intestinal metaplasia in the stomach." (PMID 25295732, 2014).
glioma (3 papers, 2012 to 2022). A benign or malignant brain and spinal cord tumor that arises from glial cells (astrocytes, oligodendrocytes, ependymal cells). "In glioma, REG4 expression was significantly higher in tumor than normal brain tissues." (PMID 36172286, 2022).
acute pancreatitis (2 papers, 2024). An acute inflammatory process that leads to necrosis of the pancreatic parenchyma. "Regenerating gene family member 4 (Reg4) has been implicated in acute pancreatitis, but its precise functions and involved mechanisms have remained unclear." (PMID 38769308, 2024). "Immunohistochemical (IHC) staining of proliferating cell nuclear antigen (PCNA) indicated fewer proliferative cells in the pancreases of Reg4−/− mice than in Wt mice, particularly during acute pancreatitis." (PMID 38769308, 2024). "Our results firstly showed that Reg4 deletion resulted in the persistence of inflammatory and cell death in acute pancreatitis, and further confirmed rReg4 could protect mice against cell death." (PMID 38769308, 2024). "In acute pancreatitis, Reg4 deletion increases inflammatory infiltrates and mitochondrial cell death and decreases autophagy recovery, which are rescued by the administration of recombinant Reg4 (rReg4) protein." (PMID 38769308, 2024).
Barrett esophagus (2 papers, 2012 to 2024). Esophageal lesion lined with columnar metaplastic epithelium which is flat or villiform. "Twenty-two proteins were associated with the risk of oesophageal cancer and/or oesophageal adenocarcinoma, including REG4 and ST6GAL1 [2.02 (1.66–2.45) and 1.83 (1.53–2.19)]." (PMID 38750076, 2024).
breast carcinoma (2 papers, 2023 to 2024). "However, REG4 was three times higher in dense breasts as compared to nondense breast, indeed suggesting a role in normal breast physiology and possibly in breast cancer initiation and progression." (PMID 37064098, 2023).
colorectal tumors (2 papers, 2015 to 2023). "We next examined REG4 expression in human colorectal tumors and adjacent non-tumor tissues by qRT-PCR analysis." (PMID 26387746, 2015).
lung adenocarcinoma (2 papers, 2020 to 2023). A carcinoma that arises from the lung and is characterized by the presence of malignant glandular epithelial cells. "It has also been found that regenerating family member (REG4) is highly expressed in KRAS-mutant lung adenocarcinoma, and that silencing REG4 can inhibit cancer cell proliferation and genesis, making it a potential therapeutic target." (PMID 36675641, 2023). "REG4 promotes the progression in KRAS mutant lung adenocarcinoma cells progression and can be used as a novel biomarker in lung adenocarcinoma subtype." (PMID 33489872, 2020). "Expression of REG4 was significantly upregulated in a mutant KRAS-dependent manner in both colorectal stem cells and cancer tissues harboring APC mutation, consistent with another study with REG4 overexpression in KRAS mutant lung adenocarcinoma." (PMID 33489872, 2020). "Elevated in KRAS mutant lung adenocarcinoma with low expression of TTF-1; Seliencing REG4 reduced cancer cell proliferation and tumorigenesis via blocking G2/M transition." (PMID 33489872, 2020). "Moreover, REG4 was also upregulated in KRAS-mutant lung carcinoma and thus, is a novel biomarker in the lung adenocarcinoma subtype." (PMID 33489872, 2020).
lung carcinoma (2 papers, 2013 to 2020). "However, further studies are needed to clarify the role and underlying mechanisms of REG4 in cell proliferation and division and its potential therapeutic value in lung cancer." (PMID 33489872, 2020). "Regenerating islet-derived type 4 (REG4), a member of the calcium-dependent lectin gene superfamily, is abnormally expressed in various cancers, such as colorectal, gastric, gallbladder, pancreatic, ovarian, prostate, and lung cancer." (PMID 33489872, 2020). "Silencing REG4 reduced cancer cell proliferation and tumorigenesis in vivo and in vitro by blocking G2/M transition, suggesting an important role of REG4 in KRAS-driven lung cancer pathogenesis." (PMID 33489872, 2020).
metastatic disease (2 papers, 2010 to 2021). "We found that Reg4 expression is associated with larger tumors and higher mortality in metastatic disease, but not with recurrence risk per se." (PMID 33659040, 2021).
mucinous ovarian tumor (2 papers, 2015 to 2016). "According to our results REG4 protein is secreted into circulation by mucinous ovarian tumor cells and can be detected with an ELISA-based test." (PMID 26981633, 2016). "As expected based on the in silico data, REG4 was highly expressed only in malignant mucinous ovarian tumors." (PMID 26981633, 2016). "However, the qRT-PCR analysis of REG4 mRNA expression from fresh frozen mucinous ovarian tumors identified samples with intermediate or low expression, yet no expression was detected in samples from serous ovarian tumors." (PMID 26981633, 2016).
neuroendocrine tumors (2 papers, 2014 to 2022). "We recently reported co-expression of REG4 with the neuronal transcription factor Hath-1 (atonal, Math-1) in neuroendocrine tumors." (PMID 25295732, 2014).